AFP (alpha fetoprotein)
Diseases named in the same sentence as AFP in open-access papers (continued):
Sharing a sentence is not in itself a finding about the gene and the disease.
tumor (continued). "In the case reported in this present study (this 58-year-old male patient), both the continuous shrinking of tumor size in the MRI scans and the rapidly decreasing AFP levels during sorafenib treatment indicate that the CR of advanced HCC was induced by sorafenib." (PMID 25649133, 2015). "In addition, some studies have showed a correlation between elevated AFP serum levels and neoplasm size or the degree of differentiation and etiology." (PMID 25822740, 2015). "In one of the study, poor correlation between CD4+CD25+ Tregs and tumor marker AFP was reported." (PMID 25767469, 2015). "In addition, several studies have previously shown that the level of AFP, tumor size and AST level were related to the DFS and/or OS in patients with HCC." (PMID 26125229, 2015). "In multivariate analysis, the BMI class was also found to be a significant independent impact factor for overall survival (p = 2.2 × 10−8), age, alpha-fetoprotein level, Child–Pugh score, treatment strategy, antiviral treatment, extrahepatic metastasis, and tumor infiltration of the portal vein." (PMID 26444667, 2015). "AFP is a classical biomarker, and an increase in AFP serum level correlates with tumor size." (PMID 26487969, 2015). "In multivariate analysis, BMI class was also found to be a significant independent impact factor regarding overall survival (p = 2.2 × 10−8), age, AFP, Child–Pugh score, treatment strategy, antiviral treatment, extrahepatic metastasis, and tumor infiltration of the portal vein." (PMID 26444667, 2015). "Tumor differentiation (hazard ratio [HR] 0.404, 95% CI 0.203–0.792, P = 0.008), AFP (HR 0.134, 95% CI 0.029–0.616, P = 0.01) and administration approach to NAC (HR 2.148, 95% CI 1.138–4.053, P = 0.018) were found to be significantly associated pathological response." (PMID 26620627, 2015). "In contrast to fetal AFP, tumor-secreted AFP is differentially glycosylated." (PMID 26199728, 2015). "Both OPN and AFP levels were significantly increased with advancing BCLC tumor staging." (PMID 26122937, 2015). "Alpha fetoprotein (AFP) level can serve as a useful tumor marker for HCC diagnosis." (PMID 25761179, 2015). "The significant increased HCC early recurrence risk were observed in patients with the combinations of higher risk genotypes and higher serum AFP level advanced tumor stage, poor tumor differentiation, or no TACE treatment." (PMID 25894340, 2015). "Both DCP and AFP values increased significantly with increasing tumour sizes (p = 0.03)." (PMID 26341083, 2015). "Serum levels of tumor markers, AFP, NSE, and CEA, were increased as shown in the previous reports." (PMID 26075125, 2015). "In fact, the AFP gene is differentially modulated by retinoic acid in tumor cell lines." (PMID 25822740, 2015). "In our study, promoter of the HCC tumor marker AFP was used to ensure the HCC specificity." (PMID 25691059, 2015). "It is well known some tumor biomarkers like AFP, CEA, and CA19-9 may reflect cancer cells' growth, differentiation, invasion and metastasis to some degree." (PMID 26057470, 2015). "Since a large number of tumours express AFP-receptors in addition to normal hepatocytes, AFP could be seen as a death factor, highly selective against tumour cells but completely non-toxic to normal cells." (PMID 26158863, 2015). "Compared to patients who had low peritumoral HBsAg expression, significantly more patients with high peritumoral HBsAg expression had tumor size ≥ 5 cm (p = 0.008), microvascular invasion (p < 0.001), Edmondson grade I and II (p = 0.026), and high level of AFP (p = 0.015)." (PMID 26515593, 2015). "Second, interpretation of AFP normalization could be ambiguous because of variable patient and tumor characteristics." (PMID 26681337, 2015).
tumor (continued). "Furthermore, in a multivariable Cox regression model, including the prognostic factors used in the IGCCC model, low RBM3 expression was an independent predictor for treatment failure, when tumor markers (AFP, HCG and LDH) were entered as continuous variables." (PMID 25811459, 2015). "Based on the hypothesis that AFP levels reflect the tumor activity and burden, this marker has been frequently measured during the treatment." (PMID 26252472, 2015). "Additionally, the decrease of AFP and HBV level is the main cause of the reduction of the tumor burden caused by the surgical removal of the lesion." (PMID 26515587, 2015). "Tumor cells also showed diffuse immunoreactivity for AFP and focal strong immunoreactivity for hCG." (PMID 25886790, 2015). "The goal of the present study was to determine whether AFP can regulate the expression of CXCR4, a chemokine receptor that has been closely associated with tumor cell invasion and metastasis and the underlying mechanisms." (PMID 25815363, 2015). "In conclusion, our results suggest that changes in intra-tumor blood flow, AFP levels and remnant liver function after 2 weeks of sorafenib therapy may be useful for predicting outcomes and anti-tumor response in patients with advanced HCC." (PMID 26421430, 2015). "Similarly, the mean AFP values ranged from 599 ng/ml for tumour sizes < 3 cm to 264, 016 for tumour sizes > 10 cm." (PMID 26341083, 2015). "In the present study, we investigated the relationship between the early clinical response in intra-tumor blood flow on CE-CT, AFP levels and remnant liver function after 2 weeks of sorafenib treatment and the outcomes and anti-tumor response in patients with advanced HCC." (PMID 26421430, 2015). "CCAT1 upregulation is correlated with tumor size, microvascular invasion, and AFP." (PMID 25884472, 2015). "Serum AFP is currently the most widely used sero-logical tumor marker for HCC diagnosis." (PMID 26099202, 2015). "Previous studies documented that AFP-positive tumor cells have some properties of HCC CSCs." (PMID 25668819, 2015). "Univariate analysis identified the following factors as associated with higher incidence of tumor recurrence after curative hepatectomy: AFP level ≥400 ng/mL (P = 0.015), multiple tumors (P = 0.002), tumor size >5 cm (P < 0.001), BCLC B stage (P = 0.001), and major resection (P < 0.001)." (PMID 25965529, 2015). "Therefore, AFP is a useful tumor marker in the diagnosis of tumors, such as hepatocellular carcinomas, hepatoblastoma, and yolk sac tumors." (PMID 25962419, 2015). "The peritumoral Cbl was also associated with prognosis even in HCC subgroups with small tumor size, negative AFP, without microvascular invasion and negative HBeAg." (PMID 26474280, 2015). "In the univariate analyses, directions of the hazard ratios for age, sex, CPS, MELD, bilirubin, albumin, tumor number, tumor size, AFP, extrahepatic metastasis, and vascular invasion were in agreement with the results of the MESIAH, though their magnitudes were slightly different." (PMID 26488298, 2015). "However, thus far, few studies have attempted to identify the linkage of intracellular AFP with tumor invasion and metastasis, and the intrinsic mechanisms involving the correlation between AFP and CXCR4 have never been investigated." (PMID 25815363, 2015). "Multivariate analyses revealed that the following factors had significant effects on OS: AFP normalization (hazard ratio [HR] = 0.31; 95 % CI, 0.14–0.70; p < 0.005); age (HR = 1.08; 95 % CI, 1.03–1.14; p < 0.004); and tumor size (HR = 1.66; 95 % CI, 1.14–2.40; p < 0.008)." (PMID 26681337, 2015). "However, further research clarified the discrepancies by showing that the sensitivity of DCP and AFP vary according to tumour sizes." (PMID 26341083, 2015). "Future studies regarding serum protein induced by vitamin K absence or antagonist-II (PIVKA-II) could reveal the usefulness of this tumor marker for HCC patients with a normal AFP level." (PMID 26681337, 2015).
tumor (continued). "AFP is a tumor marker for HCC and had been used in the clinical practice for a long time." (PMID 25886790, 2015). "In week 5, MRI scans showed that the size of the tumor lesion declined by 39.8% to 7.5 cm × 5.4 cm × 5.7 cm; necrosis occurred in partial tissues of the tumor mass, as indicated by a clearer edge; and AFP levels declined by more than 50%." (PMID 25649133, 2015). "In the multivariable Cox regression models, among all 13 variables tested, 8 variables (tumor size, tumor capsule, pathological grades, AFP, ALB, PT, TBIL, and tumor number) were independent risk factors for OS and were incorporated into the nomogram to predict survival for an individual." (PMID 25776856, 2015). "Patients with high levels of DCP and low levels of AFP were reported to have large tumours more than 3 cm compared with that of small tumours less than 2 cm, and a somewhat higher frequency of moderately to poorly differentiated HCC compared with that of well differentiated HCC." (PMID 26341083, 2015). "Furthermore, early HFSR, rapid decline of AFP levels and rapid tumor shrinking are the previously observed parameters of sorafenib’s curative effects." (PMID 25649133, 2015). "Multivariate Cox regression analysis showed that serum alpha fetoprotein (AFP) level, tumor differentiation, TNM stage, BCLC stage and PVTT had significant influence on overall survival (OS) and recurrence-free survival (RFS) for HCC patients (P < 0.01 for all)." (PMID 25826294, 2015). "AFP-producing cancer is defined by positively stained tumor of anti-AFP monoclonal antibody." (PMID 25962419, 2015). "Furthermore, early HFSR, rapid decline of AFP levels and rapid tumor shrinking observed by imaging are known parameters describing sorafenib’s effects." (PMID 25649133, 2015). "The serum AFP levels apparently correlated with the tumor burden and increasing AFP levels might give a warning for timely interventions." (PMID 25886790, 2015). "Although CSF tumor markers such as AFP and hCG may be useful for diagnosing CNS GCT in some patients, the lack of such markers does not preclude the diagnosis of a GCT." (PMID 25045548, 2014). "AFP increasing may predict tumor progression and a relative poorer survival in patients with advanced HCC who receive sorafenib." (PMID 25431715, 2014). "We next analyzed the correlation between miR-106b expression and the clinicopathological characteristics of HCC, including patients’ age, gender, HBsAg, Child-Pugh classification, serum AFP level, tumor size, tumor number, vascular invasion, histological grade (Edmondson-Steiner) and TNM stage." (PMID 25466449, 2014). "Up to now, although serum alpha-fetoprotein (AFP) level is a useful tumor marker for the detection and monitoring of HCC, the false negative rate with AFP level alone may be as high as 40% for patients with early stage HCC." (PMID 24993656, 2014). "Our new prediction model consisted of four variables: LS value, activity grade, presence of multiple tumors, and ICG R15, but other risk factors such as vascular invasion, tumor differentiation, and preoperative AFP level were not included in our model." (PMID 24910997, 2014). "Multivariate analysis results showed that miR-141 expression, tumor size, tumor grade, metastasis and serum AFP might play a role in predicting the overall survival in HCC patients." (PMID 24551096, 2014). "Serum AFP level may thus be useful for monitoring treatment response, and has been suggested to be directly related to tumor size." (PMID 24993566, 2014). "Serum alpha fetoprotein (AFP) has been the most widely used tumor marker for HCC." (PMID 25546659, 2014). "In addition, a multivariate analysis demonstrated that ATAD2 status, the tumor size, metastasis and the AFP status were significant prognostic factors for HCC patients." (PMID 24552534, 2014). "The level of serum AFP, a tumor marker, was elevated (6,283 ng/ml)." (PMID 24959228, 2014).
tumor (continued). "In this case, the tumor cells were positively stained for CgA and Syn (the immunological markers for tumors derived from the neuroendocrine system) and negatively stained for AFP." (PMID 25120653, 2014). "No published studies have investigated whether pre- and post-treatment serum AFP levels predict tumor recurrence size in patients who underwent HR, TACE, and RFA." (PMID 24993566, 2014). "Moreover, AFP, number of tumor nodes, tumor size, metastasis of distant organs and lymph nodes, and vascular invasion of the portal vein and hepatic vein were proven to be significant predictors of survival in our multivariate analysis." (PMID 25133493, 2014). "Tumor response, metastases formation, and alpha fetoprotein (AFP) levels were measured." (PMID 25256830, 2014). "Univariate analysis demonstrated that Serum AFP level (P = 0.041), tumor size (P < 0.001), vascular invasion (P = 0.001), histological grade (P = 0.048) and TNM stage (P = 0.004), and miR-106b expression (P = 0.004) were significantly associated with overall survival of HCC patients." (PMID 25466449, 2014). "Serum AFP >1000 ng/mL is uncommon with tumors measuring <2 cm in diameter, whereas AFP may rise progressively to 1000–10,000 ng/mL as a tumor increases to >5 cm in diameter." (PMID 24993566, 2014). "More interestingly, patients with TRIM24 overexpression showed poor differentiation (P = 0.004), higher level of AFP (P = 0.036), higher incidence of intrahepatic metastasis (P = 0.004) and recurrence (P = 0.000006), and shorter Tumor-free survival time (P = 0.002)." (PMID 24409330, 2014). "The results revealed that a high level of miR-130b expression was correlated with serum AFP level, HBsAg status, tumor size, high histologic grade, and high TNM stage, suggesting that miR-130b might be involved in the carcinogenesis and metastasis of HCC." (PMID 25123453, 2014). "Serum AFP was the most useful tumor-marker reflecting tumor burden in HCC." (PMID 24516635, 2014). "Besides CTSL expression level, age, tumor size, serum AFP, stage, tumor recurrence and tumor differentiation were also significantly correlated with overall survival in univariate analysis." (PMID 25384089, 2014). "Overall, the C-KIT+/EpCAM+/E-cadherin+/K7−/K19−/AFP−/albumin− immunotype suggested that the present tumor may have originated from transformed C-KIT+/EpCAM+ DE-like cells, which are more primitive and undifferentiated than bipotential HPCs." (PMID 25202388, 2014). "Notably, the concurrent methylation of CDH1, GSTP1 and a few other genes were found to be significantly associated with levels of AFP, recurrence free survival (RFS) and tumor numbers." (PMID 24635883, 2014). "They reported about significantly better 3-year survival rate in the sirolimus-group (86%) compared to the Tac-population (56%; P = 0.04), although risk profiles with respect to MVI, poor tumor grading, and AFP levels were not different between the patients." (PMID 27335840, 2014). "Tumor markers (i.e., AFP, carcinoembryonic antigen/CEA, and cancer antigen/CA 19-9) are usually in the normal range; however, vascular endothelial growth factor expression was identified in all specimens from a cohort of six patients with HEHE at a single center (100%)." (PMID 25276467, 2014). "A multivariate analysis showed that the presence of EHM was an independent predictor of short OS (adjusted HR, 1.74; 95% CI, 1.39–2.17; P<0.001) after adjustment for Child-Pugh classification, AJCC T classification, tumor response (according to mRECIST), and serum alpha-fetoprotein level." (PMID 25427152, 2014). "The ratio of serum AFP level to tumor diameter may be a better predictor of recurrence after curative resection than serum AFP level alone." (PMID 24993566, 2014).
tumor (continued). "Downregulation of ANGPTL4 mRNA in HCC was significantly associated with advanced HCC stage, presence of venous infiltration, higher AFP level, poor differentiation, appearance of tumor recurrence, and poor postoperative overall and disease-free survivals of HCC patients." (PMID 25148701, 2014). "These patients had higher prevalence of HBV infection, very well-preserved liver function, lower serum AFP level, better general well-being, smaller tumor burden with more solitary nodule, lower rate of vascular invasion and more frequently treated with curative interventions." (PMID 24906132, 2014). "Several study groups recently proposed staging systems for HCC based on the extent of tumor and the underlying liver function, such as the Cancer of the Liver Italian Program (CLIP) score (based on tumor size), serum AFP level, Child-Pugh functional class, and portal vein thrombosis." (PMID 24993566, 2014). "Additionally, replating assays and immunocytochemical analyses of EpCAM and AFP indicated that GPC3 regulated tumor-initiating HCC cells." (PMID 24454751, 2014). "Multivariate analysis revealed that tumor diameter (P = 0.045, hazard ratio [HR] = 0.228, 95% confidence interval [CI]: 0.054-0.968) and pretreatment serum alpha-fetoprotein level (P = 0.024, HR = 2.239, 95% CI: 1.114-4.500) were independent predictors for long-term survival." (PMID 24410841, 2014). "In addition, the elevated nucleolin expression was markedly correlated with advanced tumor stage (P = 0.001), high tumor grade (P = 0.02) and serum AFP level (P = 0.008)." (PMID 25230759, 2014). "Univariate analysis identified AFP, maximum tumor size, tumor number, vascular invasion of portal vein and hepatic vein, tumor differentiation, distant organ metastasis and lymph node metastasis as significant predictors of survival in patients with HCC after resection." (PMID 25133493, 2014). "Serum AFP is useful as a prognostic indicator for HCC patients at the time of tumor diagnosis." (PMID 24603710, 2014). "Moreover, serum assays for tumor markers, including AFP, cancer antigen 199 and carcinoembryonic antigen yield normal results." (PMID 25120671, 2014). "Normal tumor markers levels, namely AFP and CA125, are suggestive of a benign cyst." (PMID 23826706, 2013). "Other candidate serological tumour markers have been proposed, such as lens culinaris agglutinin reactive AFP (AFP-L3), des-γ-carboxy prothrombin (DCP), protein-induced vitamin K absence or antagonist II (PIVKA-II) and golgi protein 73, which have been used in some but not all clinical settings." (PMID 23527199, 2013). "Furthermore, we demonstrated that low level of 5 hmC in HCC was correlated with tumor size and AFP level." (PMID 23671639, 2013). "Although AFP levels might be elevated in patients with chronic liver disease, it seemed difficult to differentiate a benign tumor with abnormal AFP from a malignant hepatic lesion using only laboratory tests and non-invasive or micro-invasive procedures." (PMID 24059753, 2013). "Interestingly, when tumor burden was high, reflected by high AFP level (≥400 ng/mL), the effectiveness of S-LRTs became more prominent in improving OS and PFS." (PMID 24155932, 2013). "Tumor markers (AFP, CEA, CA 19–9 and CA 125) were normal preoperatively in all patients." (PMID 24289652, 2013). "Similarly, decrease miR-20a expression (HR = 4.281, P = 0.013), tumor size (HR = 1.253, P = 0.014), pre-LT serum AFP level (HR = 2.235, P = 0.028) and micro-vascular invasion (HR = 3.643, P = 0.012) significantly affected RFS of HCC patients following LT." (PMID 23594563, 2013). "Pre-transplant status, as judged by number of tumor nodules, size of largest tumor, preoperative AFP level and neoadjuvant treatment, significantly differed between the HBV-HCC and HCV-HCC groups, and may have influenced the survival rates." (PMID 23613886, 2013).